WIPF3 (WAS/WASL interacting protein family member 3)
Description:
May be a regulator of cytoskeletal organization. May have a role in spermatogenesis (By similarity).
Synonyms: CR16; FLJ36931
Tractability: PROTAC: ubiquitination databases record sites on it; its protein half-life has been measured.
Gene: Protein-coding gene on chromosome 7 (29,806,486 to 29,917,061, forward strand). Ensembl gene ENSG00000122574.
Subcellular location: Cytoplasm
Subcellular location (Human Protein Atlas): Mitochondria
Pathways (Reactome):
Signal Transduction: CDC42 GTPase cycle; RAC1 GTPase cycle; RHO GTPases Activate WASPs and WAVEs
Disease: FCGR3A-mediated phagocytosis
Immune System: Regulation of actin dynamics for phagocytic cup formation
Gene Ontology:
Molecular function: protein binding; actin binding; alpha-tubulin binding
Biological process: Arp2/3 complex-mediated actin nucleation; endocytic recycling; exocytosis; retrograde transport, endosome to Golgi
Cellular component: cytosol; early endosome; recycling endosome; WASH complex; cytoplasm
Genetic constraint (gnomAD): Loss-of-function variants: 31 observed, 35.8 expected, observed/expected ratio (o/e) 0.87, 90% interval 0.65 to 1.17. The synonymous counts are far from expectation, so gnomAD's model fits this gene poorly and the ratio says little. Missense variants: 618 observed, 506.88 expected, observed/expected ratio (o/e) 1.22, 90% interval 1.14 to 1.3. Synonymous variants: 277 observed, 212.74 expected, observed/expected ratio (o/e) 1.3, 90% interval 1.18 to 1.44.
Homologues: Orthologues: chimpanzee WIPF3 (99% identical), macaque WIPF3 (97% identical), dog WIPF3 (84% identical), pig WIPF3 (82% identical), guinea pig WIPF3 (80% identical), mouse Wipf3 (78% identical), rat Wipf3 (77% identical), rabbit WIPF3 (69% identical), tropical clawed frog wipf3 (34% identical), zebrafish wipf3 (29% identical). Paralogues in human: WIPF2 (34% identical), WIPF1 (31% identical).
Diseases named in the same sentence as WIPF3 in open-access papers:
WIPF3 is named in the same sentence as 11 diseases in open-access papers, as found by Europe PMC text mining. Sharing a sentence is not in itself a finding about the gene and the disease. The quoted sentences say what the papers report.
focal segmental glomerulosclerosis (1 paper, 2023). A renal disorder characterized by sclerotic lesions in the glomeruli. "Glomerular gene profiles available in NephroSeq, revealed that both ARMH4 (C14orf37) and WIPF3 were reduced in diseased kidneys, with the largest difference seen for ARMH4 in collapsing and classic focal segmental glomerulosclerosis (Coll." (PMID 36649229, 2023).
gastric cancer (1 paper, 2021). A primary or metastatic malignant neoplasm involving the stomach. "The results showed that DAZ1, WIPF3, RBPMS2, and NOVA1 were low expressed in gastric cancer (P<0.05), and KIAA0101 and COL5A2 were highly expressed (P<0.05)." (PMID 34234866, 2021).
lupus nephritis (1 paper, 2023). Glomerulonephritis in the context of systemic lupus erythematosus. "This approach identified several human podocyte markers, including ARMH4 and WIPF3, which were previously identified in genome-wide association studies for lupus nephritis and albuminuria, respectively." (PMID 36649229, 2023). "Two of the markers identified in our analyses, MYL3 and WIPF3, were GWAS hits for albuminuria, and one, ARMH4, was a hit for lupus nephritis." (PMID 36649229, 2023).
ovarian carcinoma (1 paper, 2019). A malignant neoplasm originating from the surface ovarian epithelium. "The analysis revealed that many of the embryonic and cell development genes are fairly high expressed in ovarian cancer including FOXL2, GATA4, NR5A1, AMHR2, MAL and WIPF3." (PMID 31744494, 2019).
Sepsis (1 paper, 2019). Sepsis is defined as life-threatening organ dysfunction caused by a dysregulated host response to infection. "Interestingly, several of the genes linked to glucocorticoid signaling (Arl4d, Cdkn1a, Ddit4, Fkbp5, Gjb6, Il6ra, Klf15, Nfkbia, Rhob, Sdc4, Sgk1, Sult1a1, Tob2, Wipf3) and apoptotic process were still upregulated 4 days post-sepsis." (PMID 31278440, 2019).
tumor (2 papers, 2021 to 2025). "WIPF3 encoded actin cytoskeleton protein, impacting actin remodeling and cellular invasion, thus the silencing of WIPF3 promoted tumor growth." (PMID 33552157, 2021). "ND GBM pre-surgery saliva (NDT0) showed the exclusive characterization of peptide fragments of CDA, HOPX, FABP5, WIPF3, VOPP1, AHNAK, and DAZAP1 proteins, which, to the best of our knowledge, have not been previously identified in relation to GBM tumor." (PMID 41155285, 2025).
infection (1 paper, 2021). The state of being infected such as from the introduction of a foreign agent such as serum, vaccine, antigenic substance or organism. "Whereas WIPF3 and LAMA3 that associated with pathogen infection and inflammatory diseases specifically presented in C2." (PMID 33738257, 2021).
WIPF3 also shares sentences with these, for which no sentence is quoted: atherosclerosis (1 paper); cancer (1); glioma (1); kidney disease (1).